ETV6 (ETS variant transcription factor 6)
Diseases named in the same sentence as ETV6 in open-access papers (continued):
Sharing a sentence is not in itself a finding about the gene and the disease.
bone marrow fibrosis (2 papers, 2013 to 2016).
chronic lymphocytic thyroiditis (2 papers, 2021 to 2024). "NTRK3 and ETV6 fusions showed significant associations with Hashimoto’s disease, and ETV6, also with endometriosis." (PMID 39409115, 2024). "Both NTRK3 and ETV6 fusion mutations showed a marked positive correlation with Hashimoto’s thyroiditis with an approximate 13-fold and 21-fold increased likelihood of their co-occurrence with the disease compared to other cases in the cohort, respectively." (PMID 39409115, 2024). "Further, the more conventional statistical analysis identified significant associations of NTRK3 and ETV6 fusions with Hashimoto’s disease, plus in the case of ETV6, with endometriosis." (PMID 39409115, 2024). "PTC patients with a history of Hashimoto’s disease showed a positive correlation of having NTRK3 and/or ETV6 fusion mutations as well." (PMID 39409115, 2024).
Immunodeficiency (2 papers, 2025 to 2026). Failure of the immune system to protect the body adequately from infection, due to the absence or insufficiency of some component process or substance. "IKZF1 mutations were associated with pancytopenia and immunodeficiency, while ETV6 mutations were linked to hypogammaglobulinemia." (PMID 40488176, 2025). "Strikingly, exome sequencing also revealed variants in immunodeficiency-associated genes (IRAK4, USB1), autoinflammatory disorders (PSTPIP1) and unexpected candidates like ETV6, and MAN1B1 revealing previously unrecognised pathways in SLE development." (PMID 41930824, 2026).
malignant salivary gland neoplasms (2 papers, 2024). "The patient with NSCLC harbored an SGCZ::NTRK3 fusion tumor, while the patient with salivary gland cancer harbored an ETV6::NTRK3 fusion." (PMID 38967220, 2024). "Other detected fusions were SGCZ::NTRK3 (NSCLC) and ETV6::NTRK3 (salivary gland cancer)." (PMID 38967220, 2024).
myelogenous leukemia (2 papers, 2018 to 2025). "We next compared ETV6-bound regions identified in pre-B leukemia cells (Reh) to those of normal lymphoblastoid cells (GM12878) and myelogenous leukemia cells (K562) obtained from the ENCODE project." (PMID 30341373, 2018).
oligodendroglioma (2 papers, 2022 to 2024). A well-differentiated (WHO grade II), diffusely infiltrating neuroglial tumor, typically located in the cerebral hemispheres. "Taken together, these data support that the ETV6::NTRK3 fusion present in the oligodendroglioma (grade II) could be a driver to promote tumor growth in vivo, suggesting that NTRK inhibitors may be a valuable therapeutic option to delay or avoid the need for radiotherapy in this population." (PMID 39087020, 2024).
pancreatic adenocarcinoma (2 papers, 2020 to 2023). "The A16V (C→T) mutation in PRSS1, which encodes a cationic trypsinogen and has a mutation associated with hereditary pancreatitis and pancreatic adenocarcinoma, was observed in 40% (8/20) (7/17 of ETV6 translocation-positive and 1/3 of ETV6 translocation-negative secretory carcinomas)." (PMID 31822803, 2020).
papillary carcinoma (2 papers, 2022 to 2024). A malignant epithelial neoplasm characterized by a papillary growth pattern. "ETV6::NTRK3 common in radiation-associated papillary carcinoma." (PMID 38108848, 2024).
parotid gland (2 papers, 2017 to 2024). "Based on ETV6 gene rearrangement and immunohistochemical profile, 15.4% of surgically resected parotid gland ACCi and 14.3% of cases with FNA diagnosis of parotid ACC were reclassified as SC." (PMID 28484662, 2017).
thyroid tumor (2 papers, 2022 to 2023). A benign or malignant neoplasm affecting the thyroid gland. "Four out of twenty-six NTRK-rearranged thyroid tumors were negative for Trk expression (15.4%), all carrying the ETV6/NTRK3 fusion." (PMID 35806472, 2022).
viral infection (2 papers, 2015 to 2025). "Expression of CXADR, BNIP3, or SPARCL1 was not downregulated by the ETV6/RUNX1 fusion in the absence of a viral infection (data not shown)." (PMID 41497616, 2025). "In contrast, potential sumoylated forms of ZBTB4, ZBTB10 and ETV6 appeared to increase in abundance in the ICP0-null mutant infected samples, which may be related to the overall accumulation of sumoylated species that occurs during the mutant virus infection." (PMID 26200910, 2015).
amyotrophic lateral sclerosis (1 paper, 2022). Amyotrophic lateral sclerosis (ALS) is a neurodegenerative disease characterized by progressive muscular paralysis reflecting degeneration of motor neurons in the primary motor cortex, corticospinal tracts, brainstem and spinal cord. "For example, many SOD1 mutations can cause amyotrophic lateral sclerosis (ALS), NF1 mutations can cause pediatric brain tumors, RB1 mutations can cause retinoblastoma, and ETV6 mutations can cause pediatric acute lymphoblastic leukemia." (PMID 36276986, 2022).
angiosarcoma (1 paper, 2022). A malignant tumor arising from the endothelial cells of the blood vessels.
autoimmune disease (1 paper, 2016). A disorder resulting from loss of function or tissue destruction of an organ or multiple organs, arising from humoral or cellular immune responses of the individual to their own tissue constituents. "Thus, ETV6/RUNX1 expression contributes to increased B cell tolerance, which aggravates autoimmune disease." (PMID 26919255, 2016).
Autoimmunity (1 paper, 2016). The occurrence of an immune reaction against the organism's own cells or tissues. "Thus, our study reveals a previously unrecognized synergism between ETV6/RUNX1 and BCL2 impacting on malignant disease and autoimmunity." (PMID 26919255, 2016).
B-cell lymphomas (1 paper, 2022). "Studying the relationship between ETV6 and BIRC5 in established high-grade B-cell lymphoma cell lines revealed an inverse relationship between these two proteins." (PMID 35053500, 2022). "We then took advantage of a recently published study where common subtypes of B-cell lymphomas (including DLBCL) have been comprehensively interrogated at the genomic and transcriptional level to determine whether ETV6 levels may also hold prognostic relevance in these different disease entities." (PMID 35053500, 2022).
bladder cancer (1 paper, 2022). "Bioinformatic database screening for bladder cancer followed by gene co-expression network analysis revealed six new genes (PPARD, CST4, CSNK1E, PTPN14, ETV6, and ADRM1) and several new miRNAs, including miR-124, as drivers in the development and progression of bladder cancer." (PMID 36362406, 2022).
colon adenocarcinoma (1 paper, 2014). "For colon adenocarcinoma, the somatic mutations in four genes were significantly enriched in protein pocket regions: B2M (P = 3.1 × 10-4), IFNA2 (P = 3.1 × 10-4), VAV3 (P = 6.6 × 10-4), and ETV6 (P = 1.0 × 10-3)." (PMID 25360158, 2014).
colorectal tumours (1 paper, 2016). "The mRNA level of ETV6 is significantly lower in colorectal tumours than in paired normal tissues." (PMID 27145994, 2016).
Constitutional mismatch repair deficiency syndrome (1 paper, 2021). "Germline PAX5 and ETV6 mutations carry a high risk (high penetrance) of cancer, mainly ALL7, 9, 27; bloom syndrome and constitutional mismatch repair deficiency syndrome also carry a moderate risk of ALL." (PMID 33903686, 2021).
endometriosis (1 paper, 2024). The growth of functional endometrial tissue in anatomic sites outside the uterine body. "Additionally, ETV6 positively correlated with the medical history of endometriosis." (PMID 39409115, 2024).
eosinophilic disorders (1 paper, 2025).
Ewing's sarcoma family tumors (1 paper, 2008). "The EWS-FLI-1 fusion protein is associated with 85–90% of Ewing's sarcoma family tumors (ESFT), the remaining 10–15% of cases expressing chimeric genes encoding EWS or FUS fused to one of several ets transcription factor family members, including ERG-1, FEV, ETV1 and ETV6." (PMID 18648544, 2008).
experimental autoimmune encephalomyelitis (1 paper, 2024). An autoimmune demyelinating disease of the central nervous system that is produced experimentally in animals by the injection of homogenized brain or spinal cord in Freund's adjuvant. "Moreover, ETV6 is a therapeutic target in the experimental autoimmune encephalomyelitis (EAE) mouse model." (PMID 39287981, 2024).
follicular lymphoma (1 paper, 2016). Follicular lymphoma is a form of non-Hodgkin lymphoma characterized by a proliferation of B cells whose nodular structure of follicular architecture is preserved. "Nevertheless, it is tempting to speculate that in follicular lymphoma patients (which typically display BCL2 overexpression) with strong kidney infiltration ETV6/RUNX1 target genes could be involved." (PMID 26919255, 2016). "Importantly, the ETV6/RUNX1 fusion product and the antiapoptotic protein BCL2 cooperate in the development and progression of follicular lymphoma." (PMID 26919255, 2016).
fungal infection (1 paper, 2024). "Of note, 70% of AML patients developed an IFD, while only 2.4% of ALL cases (1/42; with ETV6::RUNX1 fusion and under the high-risk protocol due to high measurable residual disease during induction) manifested an invasive fungal infection." (PMID 39057383, 2024).
germ cell tumor (1 paper, 2023). A benign or malignant, gonadal or extragonadal neoplasm that originates from germ cells. "KRAS, CDKN1B, CCND2, ETV6, and RAD52 mutations are the most common in germ cell tumors." (PMID 37958970, 2023). "The most prevalent changes in germ cell tumors are CDKN1B Amplification, KRAS Amplification, CCND2 Amplification, ETV6 Amplification, and RAD52 Amplification." (PMID 37958970, 2023).
head and neck cancer (1 paper, 2024). A primary or metastatic malignant neoplasm affecting the head and neck. "The only fusion gene detected in head and neck cancer was ETV6::NTRK3 (n = 22); in STS, ETV6::NTRK3 (n = 7) and LMNA::NTRK1 (n = 5) were common." (PMID 38925616, 2024). "The only NTRK fusion gene detected in head and neck cancer was ETV6::NTRK3 (n = 22)." (PMID 38925616, 2024). "Of 38 ETV6::NTRK3 gene fusions detected, most were found in head and neck cancers (n = 22; 57.9%) followed by STS (n = 7; 18.4%)." (PMID 38925616, 2024).
lentivirus infection (1 paper, 2020). Virus diseases caused by the Lentivirus genus. "First, we successfully overexpressed ETV6 in HCCLM3 and HuH7 cells stably transfected with PCDH-EF1-MCS-T2A-Puro-ETV6 recombinant vector by Lentivirus infection against puromycin screening." (PMID 32326970, 2020).
leukocytosis (1 paper, 2023). "All ETV6::ABL1 positive patients (n = 7; male 6/7; median age 30 years, range 20–74) presented with leukocytosis >10 × 109/l (median 62 × 109/l, range 20.9–143)." (PMID 37454239, 2023).
lupus (1 paper, 2023). "A genetic diagnosis involving a gene never associated with lupus (MAN1B1, ETV6) was identified in 2 patients, explaining part of the phenotype but not the lupus." (PMID 37848930, 2023).
malaria (1 paper, 2022). Malaria is a serious and sometimes fatal disease caused by a parasite that commonly infects a certain type of mosquito which feeds on humans. "Remarkably, hepatic Etv6 expression in response to both malaria and vaccination was very similar to that of Stat3, though the constitutive expression of Etv6 in the liver was only about 1/3 of that of Stat3, with approximately 58 above normalization level." (PMID 35214745, 2022). "Infection with blood-stage malaria induced an increase in Etv6 expression on day 1 p.i., which was significantly (p-value < 0.05) higher in vaccination-protected than unvaccinated mice." (PMID 35214745, 2022).
medullary thyroid cancer (1 paper, 2017). "This is the first study showing the results of ETV6/NTRK3 rearrangement in medullary thyroid cancer." (PMID 28181547, 2017).
metastatic tumors (1 paper, 2018). "In addition, in the Taylor prostate dataset, mean expression of the ETV6 gene was significantly lower in primary tumors and further reduced in metastatic tumors compared those in normal tissues." (PMID 29455655, 2018).
ovarian tumors (1 paper, 2013). "Co-amplified genes were also prominent in the high-risk ovarian tumors including case OC-04 with high level CCNE1 amplification and co-amplification of CCND1, CCND3, MYC and ETV6 genes." (PMID 23289505, 2013).
prostate adenocarcinoma (1 paper, 2018). "Since DU145 was derived from a human prostate adenocarcinoma metastasizing to the brain, ETV6 knockdown could reactivate the metastatic properties of DU145 to the brain." (PMID 29455655, 2018).
Sepsis (1 paper, 2020). Sepsis is defined as life-threatening organ dysfunction caused by a dysregulated host response to infection. "These transcription factors (such as CEBPB and ETV6) and miRNAs are potential targets for the treatment of sepsis." (PMID 33032623, 2020).
small cell carcinoma of the ovary (1 paper, 2023). "Moreover, paraneoplastic hypercalcemia, while being specifically associated with the ETV6::NTRK3 fusions, is also significantly associated with SMARCA4 inactivation in the majority of small cell carcinoma of the ovary, hypercalcemic type." (PMID 36690805, 2023).
thrombocytopenia 5 (1 paper, 2025). "Murine studies modeling Thrombocytopenia 5-associated germline Etv6 variants have shown reduced MPP4 mediated B cell development due to altered IL-18 and IL-13 secretion and increased inflammatory gene expression among Etv6-mutated HSC." (PMID 40925926, 2025).
uterine cancer (1 paper, 2019). Primary or metastatic malignant neoplasm involving the uterine corpus and/or the cervix. "Ultimately, in vivo validation of the roles of ETV6 expression on uterine cancer progression can be studied using uterine serous cancer-bearing mouse models through in vivo silencing of ETV6 using siRNAs." (PMID 31554806, 2019).
tumor (119 papers, 2008 to 2026). "In 2024, disease progression was observed with residual KIT mutation (VAF 1.10%) and new-onset ETV6:NTRK3 fusion (VAF 35.29%) detected by circulating tumor DNA (ctDNA) analysis." (PMID 40900786, 2025). "Adding further information to this context, a recent publication by Kodgule and colleagues showed that ERG binds to GGAA microsatellite enhancers and activates according genes in ETV6-deficient or ETV6::RUNX1-positive tumor cells." (PMID 39202339, 2024). "Lastly, in a single report of a primary pulmonary SC, FISH testing for ETV6 rearrangement demonstrated a clonal variant with an extra 5′ ETV6 signal pattern (83% of tumor cells)." (PMID 39101978, 2024). "Further molecular analysis with the Oncomine Comprehensive Assay v3 (OCAv3) and ThyroSPEC revealed an ETV6::NTRK3 fusion-positive tumor harboring an additional TERT promoter mutation c.-124C>T, with no other genetic alterations." (PMID 38642578, 2024). "Subsequent to the translocation in B-ALL cases, the wildtype ETV6 allele is often mutated or deleted implicating its tumor-suppressive function." (PMID 37377909, 2023). "Deletion of the wild-type allele of ETV6 in REH cells supported the tumor suppressor status of this gene and indicated a potential mechanism of escaping IRX3-mediated activation." (PMID 36233173, 2022). "ETV6/NTRK3 was associated with follicular tumor architecture only (OR = 10.15 (1.26–81.81), p = 0.011)." (PMID 34282777, 2021). "However, the precise role and underlying action mechanism of ETV6 in tumour glucose metabolism reprogramming remain unreported." (PMID 41631407, 2026). "The activation of EGF signalling could be involved in PCa metastasis and progression through the suppression of ETS variant transcription factor 6 (ETV6), a tumour suppressor gene." (PMID 34768647, 2021). "Consistent with this hypothesis, our data in the present study has demonstrated that tumours with the BRAFV600E mutation were significantly smaller than BRAFV600E-negative cases including RET/PTC or ETV6/NTRK3." (PMID 26584635, 2015). "Interestingly, the heterogeneous staining pattern in ETV6::NTRK3 fusion-associated PTCs tends to be stronger in the tumor periphery and becomes weaker to subdiagnostic towards the center, a phenomenon that might be dismissed as artifactual in nature and considered to be non-diagnostic." (PMID 40111709, 2025). "ETV6 functions as a transcriptional repressor, playing a crucial role in maintaining hematopoiesis while also acting as a tumor suppressor." (PMID 40725152, 2025). "Using FISH, three tumors met the criteria of ≥ 10% tumor cells with break apart signals, including the ETV6::NTRK3 fusion." (PMID 37067589, 2023). "CRISPR mediated knockout of IGF2BP1 or ETV6::RUNX1 led to reduced tumor cell survival and reversal of prednisolone resistance." (PMID 37670323, 2023). "The minimally-deleted region of 12p spans 2.75Mb, and includes the gene bodies of 18 protein-coding genes, including the tumor suppressors ETV6 and CDKN1B." (PMID 36711871, 2023). "IGF2BP1 expression was essential for tumor cell survival in multiple ETV6::RUNX1 positive B-ALL cell lines." (PMID 37670323, 2023). "Immunohistochemistry with pan-TRK antibodies confirmed the nuclear localization of the ETV6::TRKC fusion protein observed in tumor samples." (PMID 36801905, 2023). "We detected five mutated genes with low VAFs in the tumor tissue, including MYD88L265P, TNFRSF14A32V, ETV6 (multiple somatic mutations), and CCND3S259A." (PMID 36644235, 2023). "ETV6 can function as a tumor suppressor and dimerize with ETV6::RUNX1 to reduce its transforming activity." (PMID 36766699, 2023).